SPIRE2 (spire type actin nucleation factor 2)
Description:
Acts as an actin nucleation factor, remains associated with the slow-growing pointed end of the new filament. Involved in intracellular vesicle transport along actin fibers, providing a novel link between actin cytoskeleton dynamics and intracellular transport (By similarity). Required for asymmetric spindle positioning and asymmetric cell division during meiosis. Required for normal formation of the cleavage furrow and for polar body extrusion during female germ cell meiosis. Also acts in the nucleus: together with SPIRE1 and SPIRE2, promotes assembly of nuclear actin filaments in response to DNA damage in order to facilitate movement of chromatin and repair factors after DNA damage.
Synonyms: Spir-2; KIAA1832
Tractability: Antibody: UniProt places it where antibodies can reach, with medium confidence; its Gene Ontology location is reachable by antibodies, with medium confidence.
Gene: Protein-coding gene on chromosome 16 (89,818,179 to 89,871,319, forward strand). Ensembl gene ENSG00000204991.
Subcellular location: Cytoplasm, cytoskeleton; Cytoplasm, cytosol; Cell membrane; Cytoplasmic vesicle membrane
Subcellular location (Human Protein Atlas): Nucleoplasm; Intermediate filaments; Primary cilium; Vesicles
Gene Ontology:
Molecular function: microtubule binding; actin binding
Biological process: actin cytoskeleton organization; establishment of meiotic spindle localization; formin-nucleated actin cable assembly; positive regulation of double-strand break repair; actin filament network formation; cleavage furrow formation; Golgi vesicle transport; intracellular transport; polar body extrusion after meiotic divisions; vesicle-mediated transport; actin nucleation
Cellular component: cell cortex; cleavage furrow; cytoplasmic vesicle membrane; plasma membrane; cytoskeleton; cytosol
Genetic constraint (gnomAD): Loss-of-function variants: 73 observed, 65.88 expected, observed/expected ratio (o/e) 1.11, 90% interval 0.92 to 1.35. The synonymous counts are far from expectation, so gnomAD's model fits this gene poorly and the ratio says little. Missense variants: 1,188 observed, 929.4 expected, observed/expected ratio (o/e) 1.28, 90% interval 1.22 to 1.34. Synonymous variants: 535 observed, 394.66 expected, observed/expected ratio (o/e) 1.36, 90% interval 1.26 to 1.46.
Homologues: Orthologues: macaque SPIRE2 (98% identical), chimpanzee SPIRE2 (89% identical), mouse Spire2 (85% identical), rat Spire2 (85% identical), pig SPIRE2 (84% identical), dog SPIRE2 (82% identical), guinea pig SPIRE2 (81% identical), rabbit SPIRE2 (77% identical), tropical clawed frog spire2 (59% identical), zebrafish spire2 (55% identical), Drosophila melanogaster spir (31% identical). Paralogues in human: SPIRE1 (42% identical).
Diseases named in the same sentence as SPIRE2 in open-access papers:
SPIRE2 is named in the same sentence as 16 diseases in open-access papers, as found by Europe PMC text mining. Sharing a sentence is not in itself a finding about the gene and the disease. The quoted sentences say what the papers report.
epilepsy (2 papers, 2023 to 2025). A brain disorder characterized by episodes of abnormally increased neuronal discharge resulting in transient episodes of sensory or motor neurological dysfunction, or psychic dysfunction. "Reduced expression of SPIRE2 has been associated with epilepsy." (PMID 41459538, 2025). "FAM228B has been linked to mental health issues, ZNF566 to cardiovascular diseases, and SPIRE2 to cardiovascular diseases and epilepsy." (PMID 38681774, 2023). "The expression of ZNF566 and SPIRE2 might be related to cardiovascular diseases and epilepsy, respectively." (PMID 38681774, 2023).
Fanconi anaemia (2 papers, 2018 to 2023). "The 16q24.3 deletion (91 kb), contains the gene for Fanconi anemia, complementation group A (FANCA), and the gene Spire‐type Actin Nucleation Factor 2, SPIRE2." (PMID 36349425, 2023).
melanoma (2 papers, 2022 to 2024). A malignant, usually aggressive tumor composed of atypical, neoplastic melanocytes. "For example, genes in cluster 2 (SPIRE2, SPATA2L), 3 (OCA2, DBNDD1, FANCA, GAS8) and 4 (URAHP, DEF8, CPNE7, MC1R) underlie the associations between melanoma and pigmentation traits." (PMID 38308491, 2024). "SPIRE2 is both downregulated in aged skin tissue (GSE85358, Expression Ratio = 0.96, p-Value = 1.82E−02) and in melanoma skin relative to adjacent normal skin (GSE44805, Expression Ratio = 0.77, p-Value = 4.84E−02)." (PMID 35907981, 2022).
skin cancer (2 papers, 2021 to 2025). "This study puts forward a set of genes that could be prioritized in upcoming investigations (e.g. CDK10 or SPIRE2) to delve deeper into the role played by the variability in DNAm as a potentially causal risk factor for skin cancer." (PMID 33248005, 2021). "Six genes (RBM6, DNAJC18, SPIRE2, CPNE1, SEPT2, and ERAP2) presented causal associations with skin cancer." (PMID 41209561, 2025).
hearing loss (1 paper, 2019). "This study is the largest GWAS meta-analysis of ARHI to date and identified 7 associated loci, of which 5 are novel (FXYD5, IPP, SPIRE2, SPTBN1 and TRIL) and 2 have been previously related to hearing loss (ILDR1, ISG20)." (PMID 31645637, 2019).
malignant meningiomas (1 paper, 2025). "In the field of tumor research, SPIRE2 has been proven to interact with miR-195 through the ceRNA mechanism, thereby regulating fatty acid synthase (FASN) and playing a significant role in malignant meningiomas." (PMID 41459538, 2025).
infection (2 papers, 2013 to 2016). The state of being infected such as from the introduction of a foreign agent such as serum, vaccine, antigenic substance or organism. "Our analysis of S. TmSipA (SL1344, sopBsopEsopE2) identified roles for Spire1 and Spire2 in different steps of the infection process." (PMID 27627128, 2016). "As these gut epithelial cells are the primary target for host cell invasion by S. Tm, these observations suggest that SPIRE2 might also affect the infection in vivo." (PMID 27627128, 2016). "At any rate, the functional differences detected between SPIRE1 and SPIRE2 in the HeLa Kyoto and the iMEF infection assays might be of general interest, as earlier studies of SPIRE proteins have not detected significant functional differences between the different family members." (PMID 27627128, 2016). "Interestingly, SPIRE2 (but not SPIRE1) has recently been shown to promote the efficiency of host cell infection by Listeria monocytogenes." (PMID 27627128, 2016).
tumor (2 papers, 2025). "They used the extraction of exosomal mRNA and detection of mRNA expression of candidate genes related to tumor progression or invasion, such as cyclin-dependent kinase 6 (CDK6), ras homolog family member U (RHOU), and spire type actin nucleation factor 2 (SPIRE2)." (PMID 40362297, 2025).
SPIRE2 also shares sentences with these, for which no sentence is quoted: bone marrow failure (1 paper); cardiovascular diseases (1); cutaneous melanoma (1); meningioma (1); non-melanoma skin carcinoma (1); oculocutaneous albinism (1); Pigmentary retinopathy (1); pneumococcal infection (1).